MIR514A3 (microRNA 514a-3)
Synonyms: hsa-mir-514-3; MIR514-3; MIRN514-3; hsa-mir-514a-3
Gene: MicroRNA gene on chromosome X (147,284,641 to 147,284,728, reverse strand). Ensembl gene ENSG00000207867.
Homologues: Orthologues: chimpanzee ptr-mir-514-2 (100% identical), chimpanzee ptr-mir-514-2 (99% identical), chimpanzee MIR514-1 (98% identical), macaque mml-mir-514a (98% identical), dog MIR514 (75% identical), mouse Mir509 (68% identical), rabbit ocu-mir-506 (41% identical). Paralogues in human: MIR514A2 (100% identical), MIR514A1 (99% identical), MIR509-1 (82% identical), MIR514B (73% identical), MIR509-3 (68% identical), MIR506 (59% identical), MIR507 (59% identical), MIR513A2 (57% identical), MIR513B (56% identical).